AFP (alpha fetoprotein)
Diseases named in the same sentence as AFP in open-access papers (continued):
Sharing a sentence is not in itself a finding about the gene and the disease.
tumor (continued). "In all injection sites, multicellular tumor-like formations contained foci with positive cells for AFP, ASM, or GFAP." (PMID 34831039, 2021). "Individual animal immuno-PET GTV measurements strongly correlated with serum AFP concentrations (R2 of 0.90), demonstrating its reliability in assessing tumor burden and measuring tumor volume." (PMID 33580090, 2021). "First, our sample size was limited, and it was not possible to adjust for significant clinical and pathological covariates such as tumor burden on explant, presence of microvascular invasion and AFP at time of transplant." (PMID 34794390, 2021). "Between the HAS and non-HAS groups, there were statistically significant differences in terms of sex; serum AFP, carbohydrate antigen (CA)-125, and CA-724 levels; and longest tumor diameters (all P < 0.05)." (PMID 34956891, 2021). "In the three CAF isolates from HCC derived from patient 1–3 cancer stem cells (CSC) positive for CD13, CD44, CD90, CD133, OV6, epithelial cells or CSCs positive for EpCAM, or general tumor cells positive AFP were identified by immunofluorescence." (PMID 34947582, 2021). "Criteria have evolved by expanding the allowable tumor size and number to the incorporation of alpha-fetoprotein (AFP) and histologic differentiation." (PMID 34794390, 2021). "Similar to other studies, our study revealed that the tumour size, AFP level, Child–Pugh score, and BCLC stage are prognostic factors for OS and TTP." (PMID 33879085, 2021). "It possessed a worthy and promising therapeutic effect due to the improvement in the tumor biomarkers as AFP, TNF-α, Caspase- 3, VEGF, TGF-β1, CEA, and reduction of the lipid peroxidation." (PMID 34319038, 2021). "The triple therapy protocol described in this study rapidly reduced tumor load and attenuated tumor activity, manifested by a rapid decrease in AFP level and tumor volume, extensive tumor necrosis and inactivation of cancer thrombus regression." (PMID 34868921, 2021). "In our study, decreased AFP at in patients at 3 weeks of treatment, was extracted as a factor predicting the early tumor response." (PMID 34439111, 2021). "Among patients whose tumour markers were available, the mean AFP level in our group was 6,553.9 +/− 1,655 ng/mL." (PMID 34824613, 2021). "The incidence of MVI in hepatectomy or transplantation specimens has been found to increase with tumor size, the presence of multiple tumors, a high AFP level, and a high histological grade." (PMID 34503212, 2021). "According to our results, TrxR activity was generally more effective than other routine tumor markers including AFP, CEA, and CA19-9 in the diagnosis and monitoring the therapeutic efficiencies in both PLCs and MLCs." (PMID 33727662, 2021). "As expected, the proportions of patients with Child-Pugh class B or C were higher among the stage D patients, while the proportions of patients with tumor size > 5cm, AFP > 200 ng/dL, or TNM stage 3 or 4 were higher among the stage C and D patients." (PMID 33765059, 2021). "S.c. inoculation with Ad-mAFP-transduced DC, as vaccine, induced a delay of tumor-growth of AFP-positive HCC compared to controls." (PMID 34282787, 2021). "To further stratify our data into key clinical parameters that affected HCC TGR, we developed a tree model of the predictors that included age, sex, era, AFP, albumin, CP score, receipt of surveillance, and initial tumor size in the entire 191 HCC TGR cohort." (PMID 34966854, 2021). "In the final model, patients were assigned 2 points if largest tumor diameter ≥8 cm, or tumor number ≥2, 1point if main trunk was complete obstructed, or AFP ≥400 ng/ml." (PMID 34513667, 2021). "Tumor size (plasma AFP) was monitored weekly, until animals were euthanized according to humane endpoint criteria." (PMID 33747358, 2021). "The low expression of circRNA-5692 was closely correlated with abnormally high levels of AFP, history of LC, larger tumor size, and distant metastasis." (PMID 34540684, 2021).
tumor (continued). "Mechanisms of AFP overexpression and the biological characteristics of patients with tumours with high levels of AFP are not fully understood." (PMID 33531690, 2021). "But they did not found any significant correlation between UCA1 expression and serum AFP level or tumor size." (PMID 33565716, 2021). "High PNO1 expression was an independent risk factor in the poor HCC prognosis patients and significantly related to clinicopathological features, such as tumor size, AFP level, and positive rate of Ki-67." (PMID 34050137, 2021). "AFP is also another classic tumor marker, which is mainly used for predicting advanced disease and poor prognosis." (PMID 34776950, 2021). "We incorporated the AST, GGT, TB, AFP and tumor diameter into the multivariate logistic regression equation." (PMID 34234239, 2021). "Cytoplasmic AFP has been shown to promote tumor cell proliferation, inhibit cell apoptosis, and to play an important role in HCC occurrence and development." (PMID 33765973, 2021). "Circ_0091579 expression was positively correlated with the concentration of serum alpha fetoprotein, tumor size, tumor node metastasis stage, and metastasis in patients with HCC." (PMID 33817300, 2021). "Ovarian teratomas mostly share symptoms like dysgerminomas and can be characterized as abdominal pain due to ovarian torsion, bleeding, and can be diagnosed with mild elevated levels of tumor markers AFP and hCG." (PMID 33671303, 2021). "Alpha-fetoprotein (AFP) level, tumor number, arterial peritumoral enhancement, satellite nodule and peritumoral hypointensity at hepatobiliary phases in the training cohort were identified as independent risk factors for early recurrence after ablation." (PMID 34094938, 2021). "Whereas gender ALBI grade and tumor size covariates were significant in the offset regression, the covariates for ln(AFP) and micro-vascular invasion were significant when the forward selection procedure was followed." (PMID 34235600, 2021). "In a clinical study covering 892 patients with liver cancer, abnormally high METTL1 expression was significantly positively correlated with serum AFP level, tumor volume, tumor vascular infiltration, and poor prognosis." (PMID 34778277, 2021). "A risk score model for the prediction of MVI was built with preoperative TTV and AFP, which represent the tumor burden and biology, respectively." (PMID 34503212, 2021). "Hepatitis B e antigen positive, high AFP level, large tumor size, microvascular invasion, multiple tumors, and advanced TNM stage were also found associated with worse OS and shortened TTR in univariate analysis." (PMID 33446239, 2021). "Pre-transplant AFP is independently associated with post‐transplant HCC recurrence survival, suggesting that elevated levels reflect increased tumor aggressiveness that is present even with recurrent disease." (PMID 33754656, 2021). "At present, AFP is a serum tumor marker often used to monitor HCC, and it locates on the ribosomes of the rough endoplasmic reticulum of liver cells." (PMID 33971914, 2021). "90Y-DOTA-αGPC3 RIT effectively reduced tumor burden with a decrease in serum AFP and 89Zr-DFO-αGPC3 immuno-PET tumor volume compared to control." (PMID 33580090, 2021). "In the present study, the clinical indicators of tumor size and biological aggressiveness, which were reflected by the AFP level, were significant factors affecting survival and complete response rates." (PMID 34684036, 2021). "One patient with a normal alpha-fetoprotein level underwent primary tumor excision followed by adjuvant chemotherapy." (PMID 33530223, 2021). "In conclusion, clinical information (larger tumor size, higher AFP level) and CEUS LR-M are significantly correlated with the presence of MVI." (PMID 34307168, 2021). "Specifically, GINS4 expression was significantly greater in HCC patients that belong to age ≤60 years old (P = 0.011), female (P = 0.010), AFP level >400 (P = 0.007), with residual tumor (P = 0.009), relapse (P = 0.017)." (PMID 33842367, 2021).
tumor (continued). "These subclasses correlate with clinical parameters such as tumor size, cellular differentiation state, and serum AFP levels." (PMID 34073538, 2021). "In clinical samples, TIGIT expression increased with tumor dedifferentiation and with higher AFP expression." (PMID 33805268, 2021). "Tumour-infiltrating CD8low patients harboured high Serum AFP (p = 0.019), large tumor size (p = 0.028), and Lymphatic metastasis (p = 0.039)." (PMID 34149929, 2021). "After treatment, MRI showed significant reduction of the tumor mass, and AFP levels were normal for the remaining days." (PMID 33663127, 2021). "As a tumor marker of HB, serum AFP not only has important prognostic significance in the initial diagnosis, but is also one of the important therapeutic indicators during the treatment." (PMID 33849474, 2021). "In multivariate analysis, age > 70, AST > 45 IU/L, large tumor size, AFP > 400 ng/mL, and ALBI-grade migration to grade 3 were independent risk factors associated with OS in individual model." (PMID 34503135, 2021). "Other tumor biomarkers, such as des-γ carboxyprothrombin, lectin-bound AFP, glypican 3, Golgi protein 73, and Dickkopf 1, also fail to effectively improve the accuracy of diagnosis." (PMID 33869059, 2021). "The spot-like appearance of the yellow AFP/α-SMA signal indicated that it stemmed from tumor cell invadosomes, which are known to be enriched in actin and penetrating the microenvironment." (PMID 34947582, 2021). "These factors were clinical TNM stage, alanine aminotransferase (ALT), AFP, Edmondson–Steiner classification, tumor size, tumor capsule, tumor margin, and tumor number." (PMID 35096577, 2021). "Tumor AFP expression generally correlates with serum AFP, although this correlation is not absolute." (PMID 33450845, 2021). "constructed a multiplex electrochemiluminescence (ECL) immunoassay for simultaneous assessment of two unique tumour markers, alpha-fetoprotein (AFP) and carcinoembryonic antigen (CEA), using multicolor QDs as labels and graphene as a conducting bridge (CEA)." (PMID 34745974, 2021). "Of the 20 patients without tumors, 14 were tested for tumor markers; 8 of them had normal tumor marker test results, and the remaining 6 had slightly elevated levels of alpha-fetoprotein, cancer antigen 125, or cancer antigen 19-9." (PMID 33429819, 2021). "In conclusion, our study demonstrates that three tumor biomarkers, including AFP, AFP‐L3, and GP73, can be used as prognostic factors for predicting the recurrence of HCC, but liver function tests seem to have better survival prediction values." (PMID 34403527, 2021). "Univariate logistic regression analysis showed that AFP level, tumor number, tumor margin, arterial peritumoral enhancement, satellite nodule, and peritumoral hypointensity at HBP were associated with postoperative early recurrence in the training cohort." (PMID 34094938, 2021). "Aim of this study was to develop a physic-mathematical model to investigate tumor dynamics using α-fetoprotein (AFP) and protein induced by vitamin K absence-II (PIVKA-II) measures combined with digital imaging." (PMID 33922938, 2021). "The results showed that the two groups were remarkably different regarding the clinical stage, histological grade, number of tumours, AFP levels and survival status." (PMID 33300278, 2021). "Factors such as AFP, TNM staging, and liver reserve function can be used to predict the survival of HCC patients after the operation and the risk of tumor recurrence." (PMID 35155212, 2021). "It was concluded that the total CTC count was related to BCLC stage, tumor metastasis and serum AFP level." (PMID 33726759, 2021). "AFP, tumor size, tumor differentiation, tumor number, and MVI should be observed in patients who received TACE." (PMID 34745962, 2021). "Univariate analysis showed that AST (> 40U/L vs. ≤ 40 U/L), GGT (> 60U/L vs. ≤ 60U/L), AFP and tumor diameter were significantly different between the two groups (P < 0.05)." (PMID 34234239, 2021).
tumor (continued). "According to previous researches, serum total bilirubin (TBil), hepatitis B surface antigen (HBsAg), neutrophils to lymphocytes ratio (NLR), alpha-fetoprotein (AFP), and tumor maximum diameter (MD) were related to MVI." (PMID 33747956, 2021). "In the present case, immunohistochemical analysis showed that the tumor cells were positive for AFP, and the serum AFP level decreased dramatically to the normal level after resection of the tumor." (PMID 33913027, 2021). "In the present study, we found AFP >400 ng/ml, lymphocyte count <1.10 × 109/L, VEGF-A ≥138.30 pg/ml, peritumoral enhancement, irregular tumor shape, and intratumoral artery were significantly associated with MVI." (PMID 35004273, 2021). "One patient with a maximum tumor diameter of 8 cm, AFP level of 5.3 ng/mL, and PIVKA-II 500 mAU/mL survived 7.8 years after LT without recurrence until death." (PMID 33996606, 2021). "Multivariable Cox regression analyses identified that a tumor size > 5 cm and AFP > 400 ng/mL predict poorer outcomes in HCC patients." (PMID 34067711, 2021). "The results of the multifactorial analysis revealed that the independent factors for the identification of HAS were serum AFP level, M stage, and degree of tumor enhancement on CT." (PMID 34956891, 2021). "We examined the correlation between SOX2, Bax, or Bcl-2 expression with liver function tests (LFT), including AST, ALT, ALP, as well as alpha-fetoprotein (AFP) tumor marker." (PMID 34436030, 2021). "GSTP1 has been negatively correlated with tumor size and serum alpha-fetoprotein (AFP) in HCC patients while higher GSTP1 levels have been associated with longer overall survival and better prognosis." (PMID 33673113, 2021). "Many researchers, including us, have identified preoperative serum AFP concentration, tumor size, and Child–Pugh score as prognostic factors for recurrence and survival after surgery for HCC." (PMID 33671388, 2021). "Meanwhile, distant recurrence is related to de novo carcinogenesis and multiple tumor factors, such as tumor size, number of tumors, and AFP level." (PMID 34638613, 2021). "FOXP4-AS1 level was strikingly related to age, AFP, and tumour diameter (P = 0.001, P < 0.001, and P < 0.001, respectively) in the combined set." (PMID 33604387, 2021). "The tumor marker's alpha-fetoprotein mean level was 47807.56 ng/mL (±100578.37), and this elevation was found in 55.6%." (PMID 34899923, 2021). "In the univariate analysis for OS, variables with P < 0.1 including HBV, portal vein invasion, ascites, AFP, tumor capsule, tumor size, tumor number, MVI, cell differentiation, NLR, PLR, GPR, ALR and FAR, were then entered into the Cox multivariate analysis." (PMID 34535132, 2021). "The findings above suggested that EGR1 was positively associated with the tumor size, TNM staging, and the serum expression of TBIL, AST, ALT and AFP in patients." (PMID 34409922, 2021). "The results of the multivariate analysis revealed that the independent factors for differentiation were serum AFP level (P = 0.001), M stage (P = 0.038), and tumor enhancement on CT (P = 0.014)." (PMID 34956891, 2021). "Recent publications define the aggressiveness score based on four clinical parameters, i.e., tumor size, multifocality, presence of portal vein thrombus, and blood alpha-fetoprotein levels." (PMID 34683924, 2021). "Compared with these kinds of antibodies to AFP, the use of AFP as an anticancer drug conjugate by taking advantage of the specific expression of AFP in tumor cells is more feasible." (PMID 34680245, 2021). "The classical serum tumor markers AFP, HCG, and LDH are universally part of the management of patients presenting suspicious testicular lesions." (PMID 33800799, 2021). "We built a risk score model to preoperatively predict MVI using TTV and AFP, which represent the tumor burden and biology, respectively." (PMID 34503212, 2021). "For model III, the clinical nomogram model (namely, Clin) was established using AFP levels and tumor sizes." (PMID 34307168, 2021).